PPARG (peroxisome proliferator activated receptor gamma)
Diseases named in the same sentence as PPARG in open-access papers (continued):
Sharing a sentence is not in itself a finding about the gene and the disease.
tumor (continued). "The peroxisome proliferator-activated receptor (PPAR) nuclear receptors are composed of three family members: PPARα, PPARβ, and PPARγ and evidence has shown their context-specific oncogenic and tumor-suppressive roles." (PMID 33482915, 2021). "In the current investigation, we systematically analyzed PPARG mRNA expression signature, genetic and epigenetic characteristics, prognostic value, correlation with tumor-infiltrating immune cells, and related pathways in BRCA." (PMID 34567087, 2021). "Previous studies have found that some PPARγ agonists can inhibit tumor cell proliferation, induce tumor cell apoptosis, and inhibit tumor angiogenesis." (PMID 33029112, 2020). "Then we confirmed that the expression level of PPARγ of tumor-infiltrating CD8+ T cells was higher in FABP5high cells." (PMID 32611686, 2020). "The SUMOylation of lysines 107 and 395 on PPARγ suppresses its lipid-dependent tumor-suppressive activity." (PMID 32781719, 2020). "More recently, the same group showed that FABP5 inhibitors suppress PCa tumor formation and metastasis by inhibiting fatty acid uptake and PPARγ expression." (PMID 33352874, 2020). "Inhibition of tumor angiogenesis and growth in vivo by PPARγ activation with thiazolidinediones has further been reported for ovarian carcinoma, and pancreatic cancer." (PMID 32785018, 2020). "Collectively, increasing PPARG expression suppresses the miR-27b-3p oncogenic function, which plays an important role in tumor growth." (PMID 32850439, 2020). "For example, tumor cells use paracrine Wnt5a/β-catenin signaling to activate PPARγ in DCs, leading to enhanced FAO and DC dysfunction." (PMID 33086073, 2020). "PPARG is a nuclear receptor that is widely involved in the regulation of lipid metabolism, glucose homeostasis, and tumor progression due to its role as a transcription factor." (PMID 33536908, 2020). "FABP5 has also been shown to promote PCa cell invasion and tumor metastasis by facilitating PPARγ activation." (PMID 33352874, 2020). "The adipocyte differentiation factors PPARγ and C/EBPα were reduced by the tumor compared to the control group." (PMID 33086629, 2020). "Of note, TERT mRNA expression levels were not different when considering other genetic alterations present in the tumours, such as BRAF, NRAS mutations and RET/PTC or PAX8/PPARγ rearrangements (Figure A1)." (PMID 32659948, 2020). "Here the authors show that iNKT-intrinsic lipid biosynthesis is important for their function but is impaired in tumors, and its restoration with PPARγ agonist drugs promotes anti-tumor iNKT response." (PMID 31974378, 2020). "A specific BCP-mediated CB2 receptor activation has been demonstrated to be at the base for example of tumor suppression in glioblastoma where it has anti-proliferative effects and plays an anti-inflammatory activity through the modulation of NF-κB and PPARγ." (PMID 33114564, 2020). "Remarkably, the FCT tumour positive for PAX8/PPARγ rearrangement also harboured a RET/PTC1 rearrangement." (PMID 32659948, 2020). "In vivo animal studies are needed to address the efficacy of using PPARγ agonists and/or proliferation inhibitors to reduce tumor grade/stage of MIUC." (PMID 32822399, 2020). "Because this pathway regulates lipid metabolism, we analyzed the expression levels of PPARγ, a transcription factor that is involved in lipid metabolism, in three tumor cell lines (TMD, 4T1.2, and EO771)." (PMID 32128277, 2020). "By down-regulating its target PPARG, miR-27b-3p can promote tumor proliferation, migration, invasion, and metastasis in patients with TNBC." (PMID 32850439, 2020). "Peroxisome proliferator-activated receptor gamma (PPARɣ) agonists exert powerful anticancer effects by suppressing tumor growth." (PMID 33046822, 2020). "Lactic acid in tumor microenvironment reduces PPARγ expression in intratumoral iNKT cells and thereby diminishes their lipid synthesis and IFN-γ production." (PMID 31974378, 2020).
tumor (continued). "TZDs have been reported to exert anti-tumour effects, such as apoptosis induction, differentiation, and growth (proliferation) arrest via PPARγ-dependent or -independent mechanisms." (PMID 32170185, 2020). "A single injection of ApoSQ cells was found to inhibit lung metastasis in mice and enhanced PPARγ/PTEN signaling in TAMs as well as in tumor cells was observed." (PMID 33352766, 2020). "We observed that the synthetic specific PPARγ agonist rosiglitazone reduced secretion of M1 pro-inflammatory and pro-tumor M2-cytokines." (PMID 31936729, 2020). "The most extensively studied FABP in PCa, FABP5, promotes PCa cell and/or xenograft tumor growth, with inhibition of both PPARβ/δ and PPARγ suppressing these effects." (PMID 33031638, 2020). "Transwell invasion assay confirmed the enhancing effect of miR-27b-3p mimics on tumor invasion, while the PPARG agonist reduced this effect." (PMID 32850439, 2020). "Our results support the chemosensitivity-promoting role of PPARG in HSCC tumor cells, most likely by affecting both cell proliferation and cell motility pathways." (PMID 32373170, 2020). "To demonstrate that PIO enhanced iNKT cell-mediated anti-tumor immune responses in vivo by targeting at PPARγ in iNKT cells, we generated mixed bone marrow chimeric mice to delete PPARγ specifically in iNKT cells." (PMID 31974378, 2020). "Activation of PPARγ regulates the expression of multiple target genes and inhibits the proliferation or migration of tumor cells." (PMID 32328200, 2020). "Genome-wide expression profiling identified a group of genes within the angiogenesis pathway, including angiopoietin-like 4 (Angptl4), fibroblast growth factor 1 (Fgf1), and pleiotrophin (Ptn) as targets of activated PPARγ favoring tumor angiogenesis." (PMID 32785018, 2020). "Blocking CDK5/pho‐PPARγ significantly reduces CD44v+ BCSCs population in tumor tissues, thus abrogating metastatic progression in TNBC mouse model." (PMID 33240752, 2020). "PPARγ influences inflammatory processes, cell proliferation, differentiation, apoptosis and tumor angiogenesis." (PMID 32085795, 2020). "We show in this study that 20HE signaling, through Eip75B-A /- C/PPARγ, is capable to alleviate Notch tumor growth by driving intestinal progenitors into post-mitotic absorptive EC fate." (PMID 32773037, 2020). "In this context, natural and synthetic PPARγ agonists have been proven to exert potent modulatory effects in different cell types, extending the repertoire of potential cellular target of this tumor suppressor." (PMID 33352766, 2020). "By making comparisons of the PPARγ expression in protein and mRNA level, significant differences were found in tumor size, clinical stage, pathological grade, and recurrence, while age and gender showed no statistical difference." (PMID 33289586, 2020). "The activation of PPARγ with synthetic agonists, such as the TZD anti-diabetic drugs rosiglitazone and pioglitazone, have been implicated to inhibit tumor malignancy." (PMID 33352766, 2020). "The PPARγ agonist RS5444 inhibited tumor vascularization and growth of xenotransplanted anaplastic thyroid carcinomas." (PMID 32785018, 2020). "Although the exact roles of PPARγ in tumor microenvironments are still controversial, PPARγ is frequently regarded as a tumor suppressor, since numerous studies have shown that PPARγ transactivation by ligand binding induces inhibitory effects on tumor growth." (PMID 33266062, 2020). "Collectively, these data support the tumor suppressive role of PPARγ in GBM by suppressing stemness and attenuating TNFα-induced PMT." (PMID 32280134, 2020). "Natural agonists of PPARγ have confirmed anti‐inflammatory, antioxidant properties, anti‐fibrosis, anti‐tumour and metabolism regulation effects." (PMID 32031298, 2020). "Peroxisome proliferator-activated receptor gamma (PPARγ) has recently been revealed to regulate tumor microenvironments." (PMID 33266062, 2020).
tumor (continued). "The anti-cancer activities exerted by ω-3 PUFAs are also due to their ability to bind the tumor suppressor Peroxisome Proliferator-Activated Receptor gamma (PPARγ)." (PMID 32397091, 2020). "For example, the long non-coding RNA Ftx was found to promote aerobic glycolysis and tumor aggression by inducing the PPARγ pathway in HCC." (PMID 32479426, 2020). "In general, activation of PPARγ by agonists exerts inhibitory effects on tumor growth by various mechanisms, including apoptosis, cell cycle arrest and inhibitions of angiogenesis or differentiation." (PMID 33266062, 2020). "Within the tumor microenvironment, LL conditions increased macrophage recruitment and upregulated genes involved in lipogenesis (increase in Acaca, Fasn, Pparγ, decrease in Srebp-1), glucose uptake (Glut-1), and tumor growth (Vegfα, Myc, Ir)." (PMID 33302582, 2020). "As already mentioned, PPARγ antagonists have been demonstrated to abolish the beneficial effects of pomegranate extract in inhibition of tumor angiogenesis and growth." (PMID 32785018, 2020). "Encouragingly, regarding the prediction of EC occurrence, the PPARγ/ERRα ratio is superior not only to PPARγ or ERRα alone but also to currently used clinical serum tumor markers, namely, CA125, CA199, CA153, AFP and CEA." (PMID 33197888, 2020). "Biologically, PPARγ plays an important role in suppressing stemness as well as tumor growth of MES GSCs." (PMID 32280134, 2020). "PPARγ is generally believed to be a tumor suppressor as numerous in vitro studies show that PPARγ agonists (for instance thiazolidinediones) are able to inhibit tumor cell growth and/or induce differentiation in many different cancers." (PMID 33031638, 2020). "The re-expression of parvin-β in MDA-MB-231 cells inhibited tumor growth in the xenograft model and concomitantly induced the up-regulation of the PPARγ mRNA levels and its activation." (PMID 33352766, 2020). "PPARG agonists significantly reduced the tumor promoting effect of miR-27b-3p mimics, resulting in reduced weight and volume of tumor xenograft." (PMID 32850439, 2020). "In cell cultures and mouse models, the researchers found that elevated levels of the nuclear receptor promote cancer growth, but activation of PPARγ, either with drugs or by genetic means, has an opposite effect and suppresses tumor proliferation." (PMID 32280134, 2020). "The pharmacological inhibition or genetic interruption of CDK5/pho‐PPARγ truly diminished tumor development in the TNBC mouse model." (PMID 33240752, 2020). "PPARγ and C/EBPα both play a role in the terminal differentiation of adipogenesis and are both considered tumor suppressors." (PMID 32796696, 2020). "A tumor promoting effect of PPARγ has been reported in some tumors, such as liver, cancer or colon cancer." (PMID 32085795, 2020). "The here described MTMR7-PPARγ interaction complex offers a novel mode of PPARγ regulation by compartmentalization and a possible explanation for the pro- vs. anti-tumour effects of PPARγ-agonists." (PMID 32522977, 2020). "Lactic acid in tumor microenvironment reduces expression of PPARγ in intratumoral iNKT cells and consequently diminishes their cholesterol synthesis and IFN-γ production." (PMID 31974378, 2020). "The canonical Wnt/β-catenin signaling pathway, the COX-2 and peroxisome proliferator-activated receptor gamma (PPARγ) activities that operate in opposing manner have an impact on regulation of tumor growth, including GBM." (PMID 31652556, 2019). "We next analyzed the transcriptional impact of PPARG in the TCGA MIBC cohort by stratification into three major groups according to Neoplasm Disease Stage." (PMID 30845932, 2019). "For this purpose, PAMAM G3 dendrimer was conjugated with 16 celecoxib molecules (COX-2 inhibitor), 15 molecules of Fmoc-L-Leucine (agonist of PPARγ) and one tumor-targeting biotin molecule (G3-BCL)." (PMID 31652556, 2019).
tumor (continued). "A more recent study by this group demonstrates that PPARγ agonists suppress MDSC-induced tumor cell proliferation and metastatic behavior." (PMID 31212694, 2019). "Similar to PPARγ, fenofibrate-induced PPARα activation in various tumor cell lines concomitantly suppresses proangiogenic vascular endothelial growth factor (VEGF) biosynthesis and increases anti-angiogenic thrombospondin 1 and endostatin." (PMID 30925918, 2019). "It renders tumor cell growth PPARγ-dependent and modulates the tumor microenvironment to favor escape from immuno-surveillance." (PMID 30651555, 2019). "In inflammatory and tumor-derived cells, PPARγ plays a critical function in regulating PI3K signaling by modulating PTEN level." (PMID 31071176, 2019). "Activation of PPARγ pathway in LAL−/− MDSCs impaired tumor growth and metastasis in vivo as well as in vitro." (PMID 31275326, 2019). "We therefore utilized a highly immunogenic cutaneous squamous cell carcinoma (CSCC) cell line to verify a role for the well characterized PPARγ agonist rosiglitazone in promoting anti-tumor immune responses." (PMID 31212694, 2019). "The other main pathway was pathway in cancer, and the genes in this pathway can impact tumor cell proliferation (PPARG, RAF1), regulate hepatic glucose and lipid metabolism (FOXO1), and decrease the viability and invasiveness of HCC cells (RALA)." (PMID 31799078, 2019). "The effect of PPARγ activation on tumor growth was validated with subcutaneous tumor models in vivo." (PMID 30845932, 2019). "Metabolites and transcriptional factors identified as important in our study such as lactate, AAs, fatty acids, GSH and PPARG would have an immunometabolic role in the BC tumor microenvironment." (PMID 31100982, 2019). "In search of cancer cell growth inhibitors downstream circadian controlled pathways, ligands of PPARG (peroxisome proliferator activated receptor gamma) showed to be reducing tumor aggressiveness and enhancing cytotoxic action of anti-cancer agents." (PMID 31379749, 2019). "Of note, inhibition of the caspase-1/PPARγ/MCAD axis reduced tumor growth in a transgenic mouse model of breast cancer." (PMID 31060333, 2019). "Our data indicates that the PPARγ agonist rosiglitazone promotes anti-PDV tumor responses through an immune-mediated mechanism." (PMID 31212694, 2019). "When the staining intensity is expressed by the average percentage of the stained cells; in control group, 79.4 ± 3.6% of the tumour cells were stained with the anti p-PPARγ antibody." (PMID 31258834, 2019). "Compared with the unified conclusion that PPARγ inhibited the growth of various tumours, the effects of PPARα on tumour progression were diverse and depended on the tissue type or PPARα ligands." (PMID 31791289, 2019). "For example, PPARγ has been reported to play the role of both tumor promoter and tumor inhibitor in cancers." (PMID 35582567, 2019). "PC3-M cells were inoculated into the right flank of nude mice and the FABP5 inhibitor dmrFABP5 was injected subcutaneously to compare its tumor-suppressing effect with those of PPARγ antagonists and the chemical inhibitor SB-FI-26." (PMID 31258834, 2019). "Immunohistochemistry of serial sections of primary tumor tissue confirmed enhanced PPARγ (green), PTEN (green), and CD36 expression (green) upon ApoSQ injection." (PMID 30842627, 2019). "Previous studies have shown that PPARα and PPARγ agonists suppress tumor growth in different cancer cells by angiogenesis inhibition." (PMID 31089369, 2019). "The ability of UV to suppress anti-tumor immune responses as well as CHS responses is relevant to PPARγ as we have shown that Pparg-/-epi mice in the SKH-1 hairless, albino outbred background are markedly immunosuppressed using a CHS model." (PMID 31212694, 2019). "Additional experimental data on tumor growth inhibition implicate thalidomide as being involved in the PPARγ pathway." (PMID 30424016, 2018).
tumor (continued). "The tumor suppression activity of PPARγ has been intensively studied in numerous human malignancies (including breast, brain, colon, lung, pancreas, prostate and tongue malignancies) as well as observed in preclinical models." (PMID 29932104, 2018). "6-IL has been detected in tumor mammary glands from rats supplemented with I2, and this iodolipid is a specific agonist of PPARγ." (PMID 29530037, 2018). "There are several evidences about the tumor suppression role of PPARα and PPARγ, but there are also several evidences about their cancer promotion activity; instead, regarding PPARβ/δ, the majority of study conducted shows its oncogenic role." (PMID 29966227, 2018). "Ly6a/Sca-1 is a mouse stem cell and tumor-initiating cell biomarker that down-regulates several tumor suppressor pathways, including PPARγ, TGF-β and PTEN39,40." (PMID 29632317, 2018). "Multiple lines of evidence suggest that PPARγ acts as a tumor suppressor because it plays a role in inflammation and glucose metabolism in cancer." (PMID 30323259, 2018). "It is therefore not surprising that FH535 treatment not only reduces β-catenin expression but also PPARG expression in RMS tumor cells." (PMID 30568936, 2018). "Peroxisome-proliferator-activated receptors (PPARs) line up in the group of nuclear receptors and encompass three receptors PPARα, PPARγ, and PPARδ, which concertedly and multifaceted have impact on regulating tumor growth." (PMID 30424016, 2018). "Expression patterns of PPARγ in histologic different tumor tissues, both in tumor cells and adjacent stroma cells indicate histology and even tumor stage specific characteristic patterns, even, as shown, with predictive impact." (PMID 30424016, 2018). "Activated PPARγ is also anti-tumorigenic and anti-metastatic, regulating several function of cancer cells and controlling the tumor microenvironment." (PMID 29565812, 2018). "Both drugs have biochemically defined targets, lovastatin for HMGCR and troglitazone for PPARγ, and exhibit anti-tumor effects when combined in a sub-lethal concentration." (PMID 29932104, 2018). "ERBB2 cells assumed this metabolic behavior under the transcriptional control of PPARγ, and the inhibition of PPARγ decreased tumor cell viability." (PMID 29966227, 2018). "PAX8/PPARγ fusion is present in 35% of FTC tumors on average, can be overexpressed by up to 50-fold compared with endogenous PPARγ in tumor tissues and is probably the effector component of the oncogenic rearrangement." (PMID 30089490, 2018). "Conversely, PPARγ transcriptional activity encourages the expression of genes involved in tumor differentiation, TCA cycle, and FAO, which are all in agreement with the PKM1/PKM2 ratio increase." (PMID 29966227, 2018). "This review briefly describes and summarizes new molecular mechanisms of PPARγ-related tumor suppression since 2012." (PMID 29599799, 2018). "Downregulation of PPARγ by siRNA knockdown or treatment with PPARγ antagonist GW9662 has been shown to inhibit the growth of cancer cells, suggesting a tumor-promoting effect for PPARγ in these cells." (PMID 29599799, 2018). "Emerging data suggest that PPARγ acts as a tumor suppressor by inactivating NF-κB through different mechanisms." (PMID 29599799, 2018). "PPARγ and RXR agonists were demonstrated to inhibit interleukin-6 (IL-6) promoter activity and reduce MMP-2 and MMP-9 expression and activity in tumor-associated fibroblasts." (PMID 29599799, 2018). "The bidirectional crosstalk between PPARG and AR regulates growth and development both in normal and in tumor prostate, as recently highlighted." (PMID 29966326, 2018). "The positive role of PPARγ in the differentiation of TAMs is intriguing; the behavior of tumor stromal cells is affected by the PPARγ-mediated inhibition of FAO and induction of lipid synthesis." (PMID 29966227, 2018). "This synergistic action further verified that the PPARγ/LXRα/ABCA1 pathway played an important role in the anti‐tumor proliferative effect of efatutazone." (PMID 29573196, 2018).